GRK3 (G protein-coupled receptor kinase 3)
Diseases named in the same sentence as GRK3 in open-access papers (continued):
Sharing a sentence is not in itself a finding about the gene and the disease.
colon cancer (6 papers, 2017 to 2022). "Similar results were found in another study reporting that GRK3 is essential for the proliferation of SW620 colon cancer cells." (PMID 35281865, 2022). "In contrast, over-expression of GRK3 in prostate tumor cells and colon cancer promoted tumor growth and metastases through the induction of angiogenesis." (PMID 35996148, 2022). "Multivariate analyses indicated that GRK3 expression in colon cancer was an independent prognostic factor for survival." (PMID 29445249, 2017). "Our findings demonstrate the importance of GRK3 as a potential tumor progression promoter in colon cancer and its value as an independent prognostic marker of the disease." (PMID 29445249, 2017). "Here, we examine the GRK3 expression patterns and clarify the pathological significance and patient survival in colon cancer." (PMID 29445249, 2017). "The expression patterns of GRK3 in colon cancer were confirmed by real-time PCR and Western blotting analyses in frozen colon cancer tissues and different cell lines." (PMID 29445249, 2017). "Based on immunohistochemistry staining of TMAs, GRK3 was dramatically stained positive in primary colon cancer (130/180, 72.22%), whereas it was detected minimally or negative in paired normal mucosa specimens (50/180, 27.78%)." (PMID 29445249, 2017). "In the current study, GRK3 expression patterns were higher in colon cancer tissue compared with the paired adjacent normal mucosa." (PMID 29445249, 2017). "In summary, our study shows that aberrant expression of GRK3 plays an important role in promoting colon cancer progression through enhanced proliferation and reduced apoptosis." (PMID 29445249, 2017). "Results indicated that GRK3 expression was markedly elevated in different colon cancer cell lines than in the normal colonic epithelium NCM460 cells, which was identical to the results achieved from clinical specimens." (PMID 29445249, 2017). "Taken together, GRK3 positively regulated cell proliferation in colon cancer in vivo models, which correlated with the results observed in the in vitro assays." (PMID 29445249, 2017). "Collectively, these findings in vitro indicated that downregulation of GRK3 suppresses proliferation and induces apoptosis of colon cancer cells." (PMID 29445249, 2017). "Overexpression of GRK3 is an independent prognostic indicator that correlates with poor survival in colon cancer patients." (PMID 29445249, 2017). "GRK3 may be a clinical useful prognostic molecular biomarker for prognosis and a therapeutic target in colon cancer." (PMID 29445249, 2017). "Collectively, all these findings indicated that GRK3 involved colon cancer carcinogenesis and it could be possibly used as a biomarker to identify subsets of colon cancer with a more aggressive phenotype." (PMID 29445249, 2017). "Collectively, all these results indicated that GRK3 may be involved and play a critical role in colon cancer carcinogenesis." (PMID 29445249, 2017). "Furthermore, we explored GRK3 expression pattern in a panel of human colon cancer cell lines and normal colonic epithelium cells." (PMID 29445249, 2017). "Furthermore, the biology and functional study demonstrate that downregulation of GRK3 inhibited colon cancer cell proliferation rate in vitro and reduced tumorigenicity in vivo." (PMID 29445249, 2017). "Therefore, GRK3 is a key kinase and plays physiologic roles in the progression of human colon cancer." (PMID 29445249, 2017). "We report here a previously undescribed role of GRK3 in colon cancer." (PMID 29445249, 2017). "However, little work has been done to explore the role of GRK3 in colon cancer." (PMID 29445249, 2017). "Hence, a specific overexpression of GRK3 was observed in colon cancer, GRK3 potentially contributing to progression by mediating cancer cell proliferation and functions as a poor prognostic indicator in colon cancer and potentially represent a novel therapeutic target for the disease." (PMID 29445249, 2017).
colon cancer (continued). "Based on immunohistochemistry staining of tissue microarray, GRK3 was dramatically stained positive in primary colon cancer; noncancerous mucosa specimens were minimally or negative for GRK3 expression." (PMID 29445249, 2017). "Our study found that GRK3 was significantly overexpressed in 162 pairs of colon cancer tissues than in the matched noncancerous mucosa (P < 0.01)." (PMID 29445249, 2017). "Results revealed that GRK3 expression pattern was an independent prognostic indicator for the OS and DFS in colon cancer patients (hazard ratio: 0.424, 95% confidence interval: 0.226–0.797, P = 0.008 and hazard ratio: 0.453, 95% confidence interval: 0.241–0.854, P = 0.014, resp)." (PMID 29445249, 2017).
glioblastoma (3 papers, 2013 to 2017). The most malignant astrocytic tumor (WHO grade IV). "GRK3-deficient 66cl4-luc tumors appear larger in diameter than control tumors when visualized by optical imaging and necropsy, and studies by Woerner and colleagues have described an important role for GRK3 in regulating primary tumor growth in glioblastoma." (PMID 27049755, 2016). "Reduced expression of GRK3, 4, and 6 have previously been reported to increase tumor malignancy of glioblastoma, ovarian tumors, and medulloblastoma, respectively, through dysregulation of GPCR signaling." (PMID 27049755, 2016). "In the glioblastoma model specifically, decreased GRK3 expression resulted in abnormally sustained CXCR4 signaling and enhanced tumor growth." (PMID 27049755, 2016). "For example, PDGFR/Src has been shown to regulate GRK2 activity in other cell types and the suppression of GRK3 appears necessary for maximal glioblastoma cell growth." (PMID 23497290, 2013). "GRK3 also has been shown a negative regulator of cell growth in a subtype of glioblastoma, suggesting a subtype and tissue-specific role of GRK3, which may result from tumorigenic pathways or tumor microenvironment in different cancer types." (PMID 29445249, 2017). "GRK3 has previously been shown to regulate tumor growth and proliferation in glioblastoma (GBM)." (PMID 27049755, 2016).
medulloblastoma (3 papers, 2016 to 2022). A malignant, invasive embryonal neoplasm arising from the cerebellum. "siGRK2 knockdown did not affect protein level of its closest family member, GRK3, strengthening our conclusion that GRK2 contributes to growth and proliferation of medulloblastoma cell lines UW228 and Daoy." (PMID 31554835, 2019).
schizophrenia (3 papers, 2021 to 2022). A major psychotic disorder characterized by abnormalities in the perception or expression of reality. "The G protein-coupled receptor kinase (GRK) family member protein GRK3 has been linked to the pathophysiology of schizophrenia and bipolar disorder." (PMID 33976392, 2021). "The presently found striatal dopaminergic hyperreactivity in response to amphetamine in Grk3 deficient mice is also observed in a large number of imaging studies of schizophrenia subjects." (PMID 33976392, 2021). "In addition, our proteomic data from Grk3−/− mice displayed enrichment of altered levels of proteins linked to schizophrenia and bipolar disorder." (PMID 33976392, 2021). "Expression, as well as protein levels, of GRK3 are reduced in post-mortem prefrontal cortex of schizophrenia subjects." (PMID 33976392, 2021). "In young patients with schizophrenia, GRK3 had been reduced, whereas in the older schizophrenia group, GRK6 showed the greatest reduction." (PMID 34916973, 2021). "Grk3−/− mice were also tested for PPI, a murine model of sensorimotor gating deficits observed in schizophrenia patients." (PMID 33976392, 2021).
WHIM syndrome (3 papers, 2009 to 2020). "A study has shown that GRK3−/− mice exhibit numerous features of human WHIM syndrome, a rare congenital immune deficiency, indicating its potential effects on attenuating inflammatory responses." (PMID 32392242, 2020). "Thus, Grk3 deficiency has been associated with WHIM syndrome." (PMID 19956569, 2009). "Given that GRK3 contributes to the CXCL12-promoted phosphorylation at S346/347 and that GRK3 prefers acidic residues N-terminal to the phospho-site, we also generated a HA-tagged E343K mutant (HA-CXCR4-E343K), which corresponds to a recently discovered WHIM syndrome-associated mutation." (PMID 23734232, 2013). "Recently, a patient with WHIM syndrome who did not have a mutant CXCR4 (WHIM WT) was reported to have a selective decrease in GRK3 expression levels." (PMID 19956569, 2009).
heart failure (2 papers, 2016 to 2022). Inability of the heart to pump blood at an adequate rate to meet tissue metabolic requirements. "For comparison, the cardiac transcript levels of Grk3 were not increased but slightly decreased in Tg-RKIP hearts with symptoms of heart failure." (PMID 35203304, 2022).
metastatic tumors (2 papers, 2022). "In HCC, GRK3 was expressed in larger tumors and early stage diseases, whereas GRK6 was prone to expression in smaller, moderate histological grade and metastatic tumors." (PMID 35769816, 2022).
osteoporosis (2 papers, 2022 to 2023). A condition of reduced bone mass, with decreased cortical thickness and a decrease in the number and size of the trabeculae of cancellous bone (but normal chemical composition), resulting in increased fracture incidence. "Because Grk3-/- BmMSC osteogenic differentiation and proliferation are increased ex vivo, we investigated whether or not GRK3 deficiency affected mature bone development and susceptibility to osteoporosis in vivo." (PMID 35093170, 2022). "Given the proliferative osteoblastic phenotype that we observed in BmMSCs in vitro, we hypothesized that the Grk3−/− mouse would have a protective phenotype against osteoporosis and preserved bone density in aging; however, this was surprisingly not observed." (PMID 37048054, 2023). "In light of this finding, we hypothesized that the Grk3−/− mouse would have a protective phenotype against osteoporosis and preserved bone density during aging." (PMID 37048054, 2023). "We hypothesize that these in vitro findings may additionally contribute toward mechanisms underlying the enhanced hematopoiesis phenotype that we observed in the Grk3-/- mouse and appear to be less relevant in osteoporosis or mature bone development." (PMID 35093170, 2022).
Alzheimer disease (1 paper, 2023). A progressive, neurodegenerative disease characterized by loss of function and death of nerve cells in several areas of the brain leading to loss of cognitive function such as memory and language. "GRk3 also improved spatial learning and reduced memory deficits in an amyloid precursor protein (APP)/presenilin 1 (PS1) double transgenic mouse model of Alzheimer’s disease (AD)." (PMID 38139116, 2023).
Anxiety (1 paper, 2021). Intense feelings of nervousness, tension, or panic often arise in response to interpersonal stresses. "Despite a behavioral battery of 11 tests covering a wide range of behaviors relating to learning and memory, locomotor behavior, anxiety-like- and psychosis-like behaviors, Grk3−/− mice showed few differences from Grk3+/+ animals." (PMID 33976392, 2021). "Grk3−/− mice did not exhibit any overt signs of anxiety using the light-dark box paradigm, elevated plus-maze, or open-field." (PMID 33976392, 2021).
atherosclerosis (1 paper, 2021). A disease characterized by the build-up of fatty material and calcium deposition in the arterial wall resulting in partial or complete occlusion of the arterial lumen. "The functions of GRK3 and BID in atherosclerosis remain poorly investigated." (PMID 33460396, 2021).
diabetes (1 paper, 2018). "In animal models of diabetes, inhibition of GRK2 and GRK3 through these synthetic peptides rescues glucose tolerance and enhances insulin sensitivity." (PMID 30538631, 2018). "In animal models of diabetes, inhibition of GRK2 and GRK3 through synthetic peptides rescues glucose tolerance and improves insulin sensitivity." (PMID 30538631, 2018).
dilated cardiomyopathy (1 paper, 2018). Cardiomyopathy which is characterized by dilation and contractile dysfunction of the left and right ventricles. "GRK5 expression is also increased in dilated cardiomyopathy and volume-overloaded human left ventricle, whereas the expression of GRK3 remains stable in dilated cardiomyopathy and is slightly induced in patients with right ventricular volume overload." (PMID 30538631, 2018).
dysphoria (1 paper, 2022). Dysphoria is a profound state of unease or dissatisfaction. "Chavkin coworkers demonstrated that KOR agonist-induced conditioned place aversion (CPA), an animal model of dysphoria, was mediated by G-protein-coupled receptor kinase 3 (GRK3) and p38 MAP kinase, whereas KOR-mediated analgesic effects were G protein-mediated." (PMID 36408401, 2022).
gastric adenocarcinoma (1 paper, 2022). "Our genomic analysis showed that GRK3 expression correlated with poor prognosis of gastric adenocarcinoma (GAC) patients." (PMID 35996148, 2022).
gastric cancer (1 paper, 2022). A primary or metastatic malignant neoplasm involving the stomach. "This study aimed to examine the relationship between G protein-coupled receptor kinase 3 (GRK3) and gastric cancer prognosis and investigate the role of GRK3 in gastric cancer carcinogenesis." (PMID 35281865, 2022). "RNAi technology was applied to examine the effects of GRK3 inhibition on gastric cancer proliferation and spread." (PMID 35281865, 2022). "In cultured gastric cancer cells, GRK3 knockdown inhibited cell proliferation, migration, and invasion." (PMID 35281865, 2022). "Kaplan-Meier analysis with the log-rank test was employed to evaluate the relationship between GRK3 expression and gastric cancer prognosis." (PMID 35281865, 2022). "Multivariate Cox regression analysis also showed that the overexpression of GRK3 was an independent prognostic biomarker of gastric cancer (P = 0.029)." (PMID 35281865, 2022). "GRK3 is also a potential therapeutic target for gastric cancer." (PMID 35281865, 2022).
gastric tumor (1 paper, 2022). "To examine the expression status of GRK3 in GAC, we first explored TCGA dataset and found that expression of GRK3 was higher in gastric tumor tissues than that in normal tissues." (PMID 35996148, 2022).
HCMV infection (1 paper, 2017). "Network analysis of the differentially expressed genes in cord DCs, revealed among the downregulated genes after 16 h of HCMV infection several GPCRs with pro-inflammatory response function (ADORA3, ARRB1, C5AR1, CXCR4, GPR34, GPR183, GRK3, and RGS18)." (PMID 28993767, 2017).
hyperlipidemia (1 paper, 2025). "Therefore, the current study suggests that genes involved in these directly related hyperlipidemia pathways such as RAF1, GRK3 and CXCR2 were significant feature genes associated with hyperlipidemia." (PMID 41446394, 2025). "Therefore, based on previous studies, it can be speculated that GRK3 is related to the pathogenesis of hyperlipidemia." (PMID 41446394, 2025). "The hub genes such as RAF1, GRK3 and CXCR2, might be potential genetic biomarkers of hyperlipidemia." (PMID 41446394, 2025). "At the same time, the feature genes, including RAF1, GRK3 and CXCR2 may be potential genetic biomarkers of hyperlipidemia." (PMID 41446394, 2025).
Paget disease (1 paper, 2023). A malignant neoplasm composed of large cells with large nuclei, prominent nucleoli, and abundant pale cytoplasm (Paget cells). "We also show that aged mice deficient in Grk3 develop bone lesions similar to those seen in human PDB and other Paget’s Disease mouse models." (PMID 37048054, 2023).
pancreatic cancers (1 paper, 2022). "Although the correlation between GRK3 overexpression and prognosis has been reported in liver, colon, and pancreatic cancers, a consistent conclusion has not been obtained 14-16." (PMID 35281865, 2022).
prostate tumors (1 paper, 2016). "Analysis of microarray data in GSE58822 and GSE53202 revealed that GRK3 levels were significantly higher in prostate tumors of the TRAMP mice than in normal prostate tissues of wild type mice (P = 0.0043 in GSE58822 and P = 2.17E-16 in GSE53202)." (PMID 27191986, 2016). "Notably, GRK3 is overexpressed in human prostate tumors, especially in soft tissue metastases." (PMID 27191986, 2016).
psychotic disorder (1 paper, 2021). An abnormal condition of the mind that involves a loss of contact with reality. "Utilizing a sample of 70 genotyped bipolar disorder type 1 subjects (20 males and 50 females), of whom 29 had a history of psychosis, we also observed an association between genetically predicted decrease in GRK3 expression and a history of psychotic symptoms." (PMID 33976392, 2021). "The disturbance in attentional behavior and PPI seen in Grk3−/− mice are prominent features in psychotic disorders." (PMID 33976392, 2021). "To investigate if IL-1β induced KYNA increases contribute to psychosis-like phenotypes in Grk3−/− mice, we investigated PPI following administration of IL-1β ICV (0.5 ng) in wildtype mice." (PMID 33976392, 2021). "Taken together, our data suggest that Grk3−/− mice show face and construct validity relating to the psychosis phenotype with glial activation and would be suitable for translational studies of novel immunomodulatory agents in psychotic disorders." (PMID 33976392, 2021). "We here set out to examine the functional brain impact of Grk3 deletion in mice, hypothesizing that this model would be suitable for translational studies of novel immunomodulatory agents in psychotic disorders." (PMID 33976392, 2021). "Furthermore, Grk3−/− mice display face and construct validity relating to the psychosis phenotype with glial activation and constitutes an animal model suitable for translational studies of novel immunomodulatory agents in psychotic syndromes." (PMID 33976392, 2021). "To investigate the role of GRK3 expression for central KYNA levels and psychosis in humans, we used eQTL data." (PMID 33976392, 2021). "Here, we investigate functional behavior and neurotransmission related to immune activation and psychosis using mice lacking functional Grk3 and utilizing a variety of methods, including behavioral, biochemical, electrophysiological, molecular, and imaging methods." (PMID 33976392, 2021). "Furthermore, Grk3−/− mice, although not showing elevated spontaneous locomotor activity, were more sensitive to the locomotor stimulatory effects of D-amphetamine, another rodent model relevant to psychosis." (PMID 33976392, 2021).
pulmonary regurgitation (1 paper, 2019). "mRNA levels for β-adrenoceptors and G-protein coupled receptor kinases GRK2, GRK3 and GRK5 in peripheral blood mononuclear cells from patients with pulmonary regurgitation under treatment (n = 9) or not (n = 14) with betablockers." (PMID 30837872, 2019).